INS (insulin)
Diseases named in the same sentence as INS in open-access papers (continued):
Sharing a sentence is not in itself a finding about the gene and the disease.
type 2 diabetes (continued). "The root cause behind the low-grade inflammatory state seen in insulin resistant (obesity and type 2 diabetes) states is unclear." (PMID 29649324, 2018). "Some authors postulated strong association between the adipokine ratio (high leptin/adiponectin ratio) with a higher risk of type 2 diabetes, cardiovascular disease, or insulin sensitivity." (PMID 30200554, 2018). "Although the etiology of type 2 diabetes is complex and cause/consequence characteristics of associated dysfunctions have been debated, it is well established that impaired insulin action plays a critical early role." (PMID 30479775, 2018). "Both type 1 and type 2 diabetes are conditions that are associated with the loss of insulin-producing β-cells within the pancreas." (PMID 30205460, 2018). "Adiponectin is a major regulator of glucose and lipid homeostasis via its insulin‐sensitizing properties, and the reduction in this adipokine is associated with the development of metabolic syndrome and type 2 diabetes." (PMID 30156060, 2018). "Previous studies have used targeted genotyping approaches to identify variants associated with GLP-1 stimulated insulin secretion, which mostly focused on GWAS loci for type 2 diabetes or related traits." (PMID 29293525, 2018). "Collectively, these findings indicate that genetic variants that abolish ANGPTL4 function are associated with improved insulin sensitivity and glucose homeostasis and reduced risk of type 2 diabetes in humans." (PMID 29899519, 2018). "Here, the authors find that predicted loss-of-function variants in ANGPTL4 are associated with glucose homeostasis and reduced risk of type 2 diabetes and that Angptl4−/− mice on a high-fat diet show improved insulin sensitivity." (PMID 29899519, 2018). "The exposure of pancreatic islets to high glucose is believed to be one of the causal factors of the progressive lowering of insulin secretion in the development of type 2 diabetes." (PMID 30166558, 2018). "NAFLD is a strong determinant of insulin sensitivity and the development of type 2 diabetes, however, some distinct genetic causes for the dissociation of liver fat content and insulin sensitivity have been identified." (PMID 30227635, 2018). "For a long time plant food rich in polyphenols have been reported to cause effects similar to insulin in the utilization of glucose and act as good inhibitors of key enzymes like α-glucosidase associated with type 2 diabetes and lipid peroxidation in tissues." (PMID 29506517, 2018). "Obesity is strongly linked with the development of impaired insulin‐stimulated glucose uptake in skeletal muscle, which is a risk factor for type 2 diabetes." (PMID 30592185, 2018). "The quantification of oral insulin is supported by a previous study that measured oral insulin in smokers and demonstrated an increased risk of developing type 2 diabetes." (PMID 30405010, 2018). "Linoleic acid, an essential fatty acid in the omega-6 family is associated with reduced incidence of type 2 diabetes through its ability to improve sensibility to insulin." (PMID 30168097, 2018). "The double-blind Trial Comparing Cardiovascular Safety of Insulin Degludec vs Insulin Glargine in Patients with Type 2 Diabetes at High Risk of Cardiovascular Events (DEVOTE) assessed the cardiovascular safety of insulin degludec." (PMID 28913543, 2018). "Duration of treatment with insulin is a key predictor of the risk of hypoglycaemia, with rates of severe episodes rising in both type 1 and type 2 diabetes with longer treatment duration." (PMID 28660491, 2018). "Impaired insulin sensitivity is a key abnormality underlying the development of type 2 diabetes as well as several other clinical states." (PMID 29940866, 2018). "This is important because standing height in adults has been shown to relate to insulin secretion, type 2 diabetes risk, and cardiovascular disease." (PMID 29853885, 2018).
type 2 diabetes (continued). "Genes that affect insulin secretion are therefore potential susceptibility genes for type 2 diabetes." (PMID 30425305, 2018). "Chronic upregulation of pro-inflammatory cytokines is regarded a hallmark for impaired insulin secretion and increased β-cell apoptosis in the pathophysiology of type 2 diabetes." (PMID 29953508, 2018). "Type 2 diabetes is characterized by persistent hyperglycemia caused by insufficient insulin secretion to compensate for poor insulin sensitivity." (PMID 30073171, 2018). "We retrieved one case that a deletion mutation of insulin (INS) gene predicted to prolong amino acid sequence which rarely occurred in patients with maturity onset diabetes of the young (MODY)." (PMID 30334364, 2018). "The main cause of type-2 diabetes is excessive blood glucose and the inability of the body to produce enough insulin, also known as insulin resistance in insulin-targeting tissues such as liver, skeletal muscle, and adipocytes." (PMID 28932239, 2017). "Recent studies have shown that berries rich in anthocyanins improve insulin sensitivity and reduce the risk of type 2 diabetes." (PMID 28748082, 2017). "In people with advanced type 2 diabetes, the insulin secretion is reduced due to the progressing loss of the secretory function by beta cells of the pancreatic islets." (PMID 28758947, 2017). "Type 2 diabetes is a complex metabolic disorder characterized by hyperglycemia that is generally caused by defects in insulin production, secretion, and/or systemic action." (PMID 28275977, 2017). "Excess risk was found in patients with Type 2 diabetes, more marked among insulin users, especially with combined therapy." (PMID 29070034, 2017). "In the type 2 diabetes insulin naïve cohort, glargine use was associated with nominal decreases from baseline in total and small LDL and large VLDL; these changes were not seen with BIL treatment." (PMID 28587667, 2017). "Quantitative and qualitative insulin release patterns and their changes in type 2 diabetes are also associated with ultrastructural features involving the insulin granules, the mitochondria, and the endoplasmic reticulum." (PMID 28589121, 2017). "Several prospective studies have demonstrated an association between reduced insulin sensitivity and severity of cardiovascular diseases in type 2 diabetes patients." (PMID 28912840, 2017). "In the present study, we investigated the association of insulin sensitivity, assessed by the ISIMatsuda, with the QTc interval in a large Chinese population with type 2 diabetes." (PMID 28912840, 2017). "Reduced insulin sensitivity not only contributes to the pathogenesis of type 2 diabetes but is also linked to multiple metabolic risk factors and cardiovascular diseases (CVD)." (PMID 28912840, 2017). "The disrupted functional connectivity in the DMN has been shown to be inversely correlated with insulin resistance in type 2 diabetes, hinting at an underlying insulin-related mechanism." (PMID 28424581, 2017). "South Asian individuals have reduced insulin sensitivity and increased risk of type 2 diabetes compared with white individuals." (PMID 28409212, 2017). "First, we reviewed meta-GWASs published until January 2016, for the diseases ‘type 2 diabetes, coronary artery disease, hypertension’ and/or for the risk factors ‘blood pressure, obesity, plasma lipid levels, insulin and glucose related traits’." (PMID 28117839, 2017). "There was consistent support across all three MR methods for a causal effect of higher BMI on higher CHD and type 2 diabetes risk, and higher levels of fasting glucose, HbA1c, fasting insulin and triacylglycerols, together with lower HDL-cholesterol." (PMID 28889241, 2017). "In studies of 846 European individuals, each of whom had a parent with type 2 diabetes, it was demonstrated that homozygous carriers of the major C risk-allele variant had compromised pancreatic β-cell insulin secretion following an intravenous glucose load." (PMID 29157234, 2017).
type 2 diabetes (continued). "It is considered the “beneficial” adipokine, and its decline in plasma is associated with disease processes, such as obesity, INS resistant type 2 diabetes, and coronary artery disease in humans." (PMID 28261588, 2017). "The duration of insulin therapy is closely related to hypoglycemia risk in type 2 diabetes, which rises progressively as pancreatic β-cell function fails." (PMID 28824815, 2017). "Compelling data show that elevated insulin levels are associated with the development of pathological conditions such as obesity and type 2 diabetes." (PMID 29099048, 2017). "GPR40 AgoPAMs were first described by Luo as a potential therapy to ameliorate two of the major hormonal deficiencies in type 2 diabetes through the stimulation of insulin and GLP-1 secretion." (PMID 29053717, 2017). "Type 2 diabetes mellitus (T2DM) is a metabolic disorder characterized by hyperglycemia caused by either or both insulin resistance or insufficient insulin production." (PMID 28686739, 2017). "We have shown previously that reduction in adipose tissue of insulin signaling protein expression is one mechanism by which maternal diet-induced obesity leads to increased risk of type 2 diabetes mellitus (T2DM) in the offspring." (PMID 28338072, 2017). "AD development and symptoms are closely related to an insulin-resistant brain state, and type 2 diabetes mellitus is a risk factor for dementia and AD." (PMID 29156608, 2017). "Data on rates and potential risk factors for severe hypoglycemia in insulin-treated type 2 diabetes are relatively scarce and conflicting." (PMID 28913365, 2017). "In humans, insulin resistance and type 2 diabetes have been shown to predict the development of aging-related diseases and a preserved insulin action is strongly associated with longevity." (PMID 29156608, 2017). "In type-2 diabetes, in which impaired insulin secretion is a major factor in disease progression, dysregulated microRNA expression in the insulin-secreting pancreatic beta cell has been widely-implicated." (PMID 28332581, 2017). "A negative association of galactosylation and a positive association of fucosylation were seen for insulin and glucose, which are markers for diabetes type 2 and are also known to associate with inflammation." (PMID 28951559, 2017). "Increased levels of FFA have been observed in type 2 diabetes patients compared to those with normal glucose tolerance and were associated with impaired insulin signaling." (PMID 28431559, 2017). "In summary, reduced insulin sensitivity assessed by the Matsuda index is associated with an increase in the QTc interval on standard baseline 12-lead ECGs in type 2 diabetes patients." (PMID 28912840, 2017). "Our observations suggest that hepcidin is associated with gluco-toxicity-reduced pancreatic β-cell insulin synthesis in type 2 diabetes by inhibiting Pdx-1 expression." (PMID 28179377, 2017). "Previous studies have shown an association of the PPARG Pro12Ala polymorphism with improved insulin sensitivity and reduced risk of type 2 diabetes, but, in contrast, higher BMI." (PMID 29303622, 2017). "In this regard, compromised hepatic insulin extraction has been shown to constitute a risk factor for obesity, type 2 diabetes, metabolic syndrome, and fatty liver disease." (PMID 28184213, 2017). "Not only loss of early phase insulin response to glucose but also the disruption of high frequency pattern of insulin secretion during fasting is characteristic of beta cell failure in type 2 diabetes." (PMID 28316059, 2017). "Several miRNAs have also been implicated in β-cell dysfunction, thereby affecting insulin regulation in association with type 2 diabetes and potentially pancreatic cancer." (PMID 28294968, 2017). "Aggregation of islet amyloid polypeptide (IAPP), a peptide hormone co-synthesized and co-stored with insulin in pancreatic cells and also co-secreted to the circulation, is associated with beta-cell death in type-2 diabetes (T2D)." (PMID 28550295, 2017).
type 2 diabetes (continued). "In this cohort of critically ill patients with type 2 diabetes, insulin therapy was associated with enhanced secretion of c-peptide in response to stress-induced hyperglycemia." (PMID 28497374, 2017). "Some research indicates that the insulin requirement for the management of Type 2 diabetes is more strongly associated with postprandial CPI than with fasting CPI." (PMID 28881687, 2017). "Reduced insulin sensitivity, which contributes to the pathogenesis of type 2 diabetes, is closely linked to metabolic risk factors and cardiovascular diseases (CVD)." (PMID 28912840, 2017). "Chronic low-grade adipose tissue inflammation is not only a symptom of obesity but is also known to be a recognizable feature of the metabolic syndrome and a major cause of the decreased insulin sensitivity seen in type 2 diabetes." (PMID 29238337, 2017). "Among the list of probable genes, CHL1, LRFN2, RASGRP1, and PPM1K were significantly associated with insulin secretion and diabetes type 2." (PMID 28179884, 2017). "Our analysis also shows that a number of aberrant miRNAs are involved in pathways associated with energy metabolism, insulin signaling, type 2 diabetes signaling and adipocytokine signaling." (PMID 28264477, 2017). "The loss of insulin signaling or secretion as well as the loss of glycemic control are critical features that characterize type 2 diabetes (T2D)." (PMID 28869506, 2017). "Yet, regions marked by obesity and type 2 diabetes SNPs were associated with numerous significant regulatory impacts on genes within the glucose-insulin and leptin signaling pathways." (PMID 29081791, 2017). "Compared to subjects with biphasic shape, monophasic subjects had a worse insulin sensitivity, lower insulin secretion, higher 1-hour PG, and higher risk for type 2 diabetes." (PMID 29062840, 2017). "Because the GK rat is a lean insulin deficient rodent model of type 2 diabetes, we focused most of our studies on the pharmacological differences between GPR40 partial agonists and AgoPAMs on the hormonal and metabolic regulation of glucose homeostasis." (PMID 29053717, 2017). "During the follow-up period, GlycA was associated with impaired insulin secretion, hyperglycemia, incident type 2 diabetes (hazard ratio, 1.37; 95% confidence interval, 1.29 to 1.46) and CVD (hazard ratio, 1.21; 95% confidence interval, 1.12 to 1.32)." (PMID 28911155, 2017). "Type 2 diabetes mellitus (T2DM) is a metabolic disorder with symptoms of chronic hyperglycemia as a result of insulin resistance or a deficiency of insulin secretion." (PMID 28545222, 2017). "The results provided direct evidence for the role of the growth hormone, which is secreted mostly during sleep, in regulation of insulin sensitivity and in causation of dawn phenomenon in subjects with type 2 diabetes." (PMID 28352282, 2017). "A previous study had confirmed that the risk of type 2 diabetes was halved by the presence of a low-frequency allele in lncRNA-CCND2 that promoted insulin secretion." (PMID 28761781, 2017). "Some later studies suggested an inverse association of circulating insulin level and Lp(a) in patients with type 2 diabetes, and also in healthy subjects." (PMID 28510610, 2017). "Human insulin is a widely used model protein for the study of amyloid formation as both associated to insulin injection amyloidosis in type II diabetes and highly prone to form amyloid fibrils in vitro." (PMID 29182566, 2017). "Pathological conditions related to insulin fibrils formation are often associated to type II diabetes." (PMID 29182566, 2017). "Adults with higher vitamin C levels exhibited lower weight, BMI and waist circumference, and better measures of metabolic health, including HbA1c, insulin and triglycerides, all risk factors for type 2 diabetes." (PMID 28771190, 2017).
type 2 diabetes (continued). "Aged-EIIARORα KO or EIIARORα KO mice under HF diet for weeks are still insulin sensitive and glucose tolerant, suggesting that these mice are less susceptible to aged or diet-induced type-2 diabetes." (PMID 28744254, 2017). "Reduced insulin sensitivity is associated with an increase in the QTc interval in patients with type 2 diabetes." (PMID 28912840, 2017). "In comparison, type 2 diabetes is characterized by variable degrees of insulin deficiency and reduced responsiveness to insulin action." (PMID 28993722, 2017). "Exposure to maternal hyperglycemia in utero results in increased fetal growth as a result of higher fetal insulin secretion, while shared environmental factors post-birth will contribute to a higher risk of type 2 diabetes in the offspring." (PMID 28293907, 2017). "Genetic ablation of L-type Ca2+ channels in mouse β cells prevents rapid exocytosis of insulin granules and is associated with deficient insulin secretion reminiscent of human type 2 diabetes (T2D)." (PMID 28481223, 2017). "Type 2 diabetes (T2D) is a complex metabolic disorder characterized by hyperglycemia that is generally caused by defects in insulin production, secretion, and/or systemic action." (PMID 28275977, 2017). "The majority of these people suffered from type 2 diabetes (T2D), whose cause is insufficient insulin secretion in peripheral tissues." (PMID 29441120, 2017). "GlycA, IL-1RA, and hs-CRP were differentially associated with changes in insulin secretion, insulin sensitivity, and incidence of type 2 diabetes and CVD events during the follow-up of the METSIM cohort." (PMID 28911155, 2017). "This explains why early-onset type 2 diabetes was associated with a higher proportion of participants receiving insulin injections, even after adjustment was made for disease duration." (PMID 28422176, 2017). "Among subjects affected by Type 2 diabetes, association was more relevant for insulin-treated patients, especially for combined therapy users." (PMID 29070034, 2017). "The reference, clinical-only model using RLS regression with only the clinical risk factors of sex, age, BMI, fasting insulin level and family history predicted type 2 diabetes with an AUC of 0.68." (PMID 28597074, 2017). "SOCS3 is associated with the IL-6–STAT3 pathway in insulin signaling and has been reported to be increased in the skeletal muscle of severely obese or type 2 diabetes patients." (PMID 28706484, 2017). "Type 2 diabetes mellitus (T2DM) is a chronic metabolic disorder associated with deficiency in insulin secretion and action." (PMID 29150631, 2017). "This is the first study to report the gene–treatment interaction of the PON1 Q192R polymorphism and statin therapy on insulin secretion among patients with type 2 diabetes." (PMID 29233102, 2017). "In most people at risk of or with type 2 diabetes, prognosis can be improved by enhancing peripheral insulin sensitivity." (PMID 28124081, 2017). "Type 1 diabetes is caused by deficiency in insulin excretion by pancreatic beta cells whereas type 2 diabetes is a result of organs insensitivity to insulin." (PMID 27073693, 2016). "Increases in body weight and body mass index in patients with type 2 diabetes have been reported to increase the risk of cardiovascualr diseases whereas reduction in body weight increases insulin sensitivity and reduces blood pressure." (PMID 27669277, 2016). "In fact, by increasing insulin sensitivity, physical activity can reduce the risk of pathological conditions such as type 2 diabetes and metabolic syndrome." (PMID 26697506, 2016). "Reduced insulin sensitivity is one of the traditional risk factors for chronic diseases such as type 2 diabetes." (PMID 28123923, 2016). "That is, if the majority of myocytes’ insulin response is located at the lower region, then the person has a high risk of type 2 diabetes." (PMID 26950111, 2016).